HOXB13 (homeobox B13)
Description:
Sequence-specific transcription factor which is part of a developmental regulatory system that provides cells with specific positional identities on the anterior-posterior axis. Binds preferentially to methylated DNA.
Synonyms: HPC9; PSGD
Tractability: PROTAC: ubiquitination databases record sites on it.
Gene: Protein-coding gene on chromosome 17 (48,724,763 to 48,728,750, reverse strand). Ensembl gene ENSG00000159184.
Subcellular location: Nucleus
Subcellular location (Human Protein Atlas): Nucleoplasm
Gene Ontology:
Molecular function: DNA-binding transcription repressor activity, RNA polymerase II-specific; methyl-CpG binding; protein binding; sequence-specific DNA binding; sequence-specific double-stranded DNA binding; DNA-binding transcription factor activity, RNA polymerase II-specific; RNA polymerase II cis-regulatory region sequence-specific DNA binding; DNA binding
Biological process: angiogenesis; negative regulation of transcription by RNA polymerase II; epidermis development; regulation of transcription by RNA polymerase II; response to wounding; prostate gland development; regulation of DNA-templated transcription; response to testosterone
Cellular component: nucleoplasm; chromatin; nucleus; transcription regulator complex
Genetic constraint (gnomAD): Loss-of-function variants: 22 observed, 24.68 expected, observed/expected ratio (o/e) 0.89, 90% interval 0.64 to 1.27. The upper end of that interval is the gene's LOEUF score, 1.27, which puts it in group 5 of 6, group 1 being the genes least tolerant of losing a copy. Missense variants: 386 observed, 399.83 expected, observed/expected ratio (o/e) 0.97, 90% interval 0.89 to 1.05. Synonymous variants: 173 observed, 168.93 expected, observed/expected ratio (o/e) 1.02, 90% interval 0.9 to 1.16.
Homologues: Orthologues: chimpanzee HOXB13 (100% identical), macaque HOXB13 (98% identical), rabbit HOXB13 (95% identical), rat Hoxb13 (94% identical), pig HOXB13 (94% identical), mouse Hoxb13 (93% identical), guinea pig HOXB13 (92% identical), dog HOXB13 (89% identical), zebrafish hoxb13a (61% identical). Paralogues in human: HOXA13 (53% identical), HOXC13 (46% identical), HOXD13 (44% identical), HOXC11 (23% identical), HOXA11 (22% identical), HOXD11 (21% identical), HOXD4 (18% identical), HOXA10 (17% identical), HOXA5 (17% identical), HOXC4 (17% identical), HOXC9 (17% identical), HOXA4 (17% identical), and 30 more.
Diseases named in the same sentence as HOXB13 in open-access papers:
HOXB13 is named in the same sentence as 102 diseases in open-access papers, as found by Europe PMC text mining. Sharing a sentence is not in itself a finding about the gene and the disease. The quoted sentences say what the papers report.
prostate carcinoma (181 papers, 2005 to 2026). A carcinoma that arises from epithelial cells of the prostate gland. "In summary, our investigation supports a role for BRCA2 and HOXB13 mutations in prostate cancer predisposition and provides reassurance that BRCA1, RNASEL, and ELAC2 are not substantially contributory in this cohort." (PMID 40433050, 2025). "Germline variants in HOXB13 are known risk factors for prostate cancer and a recent study found an increased cancer risk in males for rectosigmoid- and non-melanoma skin cancers." (PMID 39979679, 2025). "KLK2 and HOXB13 have been reported to be strongly associated with the proliferation and metastasis of prostate cancer cells, and their expression levels were elevated in the invasive carcinoma regions." (PMID 40254832, 2025). "Overall, these data suggest a clear relationship between BRCA2 mutation carrier status and prostate cancer risk, as well as genetic variants in HOXB13 and localized prostate carcinoma." (PMID 40433050, 2025). "For prostate cancer, linkage and candidate gene studies have identified influential rare variants in a small number of specific genes, such as HOXB13 and BRCA212,13." (PMID 39971927, 2025). "HOXB13 loss promotes metastasis in prostate cancer via p300/CBP-driven lipogenesis and MMP induction, revealing a therapeutic vulnerability to p300/CBP inhibition." (PMID 41277556, 2025). "Germline mutations, such as those in BRCA1, BRCA2, and HOXB13 genes, can confer an increased risk of prostate cancer." (PMID 40432836, 2025). "Three patients carried LP variants in HOXB13, primarily linked to prostate cancer, including p.Gly84Glu substitution found in two NOA cases." (PMID 40060932, 2025). "Mutations in specific genes, such as BRCA1, BRCA2, and HOXB13, have been identified as contributors to hereditary prostate cancer." (PMID 40852019, 2025). "Our research shows that the RFLP-based detection of BRCA2 and HOXB13 mutations can enhance the diagnostic process of prostate cancer, particularly for early detection." (PMID 40433050, 2025). "The G84E mutation in HOXB13 has been identified as a significant risk factor for early-onset prostate cancer." (PMID 40852019, 2025). "Collectively, these results provide strong evidence that mutations in BRCA2 and HOXB13 are associated with an increased risk of prostate cancer and highlight their role as potential genetic markers for early detection and risk stratification." (PMID 40433050, 2025). "Men with inherited variants in particular genes, such as BRACA1, BRACA2, and HOXB13, have a higher risk of developing prostate cancer in their lifetimes." (PMID 40558499, 2025). "Cells of this cluster also expressed high levels of Cdkn2a (p16/p19) and of Hoxb13 encoding a lineage marker conserved throughout prostate cancer progression, indicating their luminal epithelial origin." (PMID 39865080, 2025). "BRCA2 and HOXB13 mutations significantly increase the risk of prostate cancer, demonstrating the predictive power of genetic testing for early diagnosis and risk management." (PMID 40433050, 2025). "The HOXB13 G84E variant confers an approximately 3–5-fold increase in overall prostate cancer risk, with even higher relative risk up to 8–10-fold for early-onset disease." (PMID 41440226, 2025). "HOXB13 plays a significant role in prostate development, and its mutation can lead to early-onset and familial prostate cancer." (PMID 41541272, 2025). "For example, in prostate cancer, the high penetrant variant HOXB13 G84E is most common in cases with the lowest PRS." (PMID 39484282, 2024). "The germline mutations of HOXB13 has strong associations with prostate cancer risk, marking it as a suitable specific biomarker for prostate cancer." (PMID 36609444, 2023). "HOXB13 is important in prostate development and this mutation was observed in 0.7-1.4% of prostate cancers, and 6% of early-onset prostate cancer." (PMID 36937425, 2023).
prostate carcinoma (continued). "Mutations in the HOXB13 gene have been associated with highly increased risk of prostate cancer, although they are responsible for only a small fraction of prostate cancer cases worldwide." (PMID 37021836, 2023). "With aoCRC, 50 patients had dMMR, 34 underwent germline testing, with 9 (25%) having a PGV (including 1 patient with HOXB13 increased risk allele for prostate cancer)." (PMID 37509234, 2023). "HOXB13-hereditary cancer syndrome, associated with mutations in the HOXB13 gene, is closely related to prostate carcinoma." (PMID 37239385, 2023). "For prostate cancer, the penetrance estimates for the associated genes are incomplete but for the HOXB13 variants the frequency is reported as > 4% in cases and 1.3% in controls." (PMID 36882784, 2023). "Prostate cancer has a genetic origin in <5% of cases, and this risk becomes higher when high penetrance genes such as HOXB13 are involved." (PMID 35785170, 2022). "The frequency of a HOXB13 G84E variant was higher among affected than unaffected men (1.4% vs. <0.4%) and for men diagnosed at a younger age or with a family history of prostate cancer." (PMID 35104804, 2022). "A study including 2,443 prostate cancer families of European descent detected at least one HOXB13 G84E mutation carrier, among 112 prostate cancer families (4.6%)." (PMID 35785170, 2022). "The inherited predisposition for prostate cancer implicates prostate cell and tissue repair (DNA double-strand break and mismatch repair genes) and regeneration (HOXB13 and putative MYC enhancer) in disease pathogenesis." (PMID 35104804, 2022). "Though HOXB13 G84E was found in studies of men with European ancestry, other founder mutations have been associated with prostate cancer in men of other ancestries: G132E for Japanese men, and G135E for Chinese men." (PMID 35104804, 2022). "More recently, a stop-loss mutation, HOXB13 X285K, was observed in a study of men with prostate cancer who were of African descent in Martinique." (PMID 35104804, 2022). "Through genetic linkage studies of men of European ancestry, variants at HOXB13, located at 17q21, were found to specifically affect prostate cancer risk." (PMID 35104804, 2022). "This African-specific variant, with an additional 95 amino acids in the HOXB13 homeodomain if translated, appears to be associated with prostate cancer at an early age in Black men." (PMID 35104804, 2022). "Among 743 Black prostate cancer patients, we identified 26 unique pathogenic (P) or likely pathogenic (LP) variants in 14 genes (including HOXB13, BRCA1/2, BRIP1, ATM, CHEK2, and PALB2) among 30 men, or approximately 4.0% of the patient population." (PMID 36446039, 2022). "Linkage studies have identified a missense substitution in HOXB13 associated with increased risk of early-onset prostate cancer." (PMID 33804961, 2021). "Our results indicate that evaluation of an additional locus sentinel, rs559612720 in SKAP1, would more fully capture prostate cancer risk of this locus than rs138213197 in HOXB13 alone." (PMID 34059701, 2021). "The association of rs559612720 and HOXB13 G84E with prostate cancer replicated across independent study populations, with genome-wide significance among combined subjects, and retaining significance when adjusted for each other." (PMID 34059701, 2021). "Genetics of prostate cancer have shown population specific features, particularly related mutations in HOXB13, NBN, and CHEK2; however mutations in BRCA2, mismatch repair genes, BRCA1, and ATM appear to contribute to risk in many populations." (PMID 34503195, 2021). "These sentinels identify heritable prostate cancer risk that is distinct from that attributable to HOXB13 G84E, but mechanistic studies are required to advance from clinical association to causality." (PMID 34059701, 2021). "Risk of prostate cancer is greatly elevated by the inheritance of a known germline mutation of HOXB13 in men of European ancestry." (PMID 34059701, 2021).
prostate carcinoma (continued). "While additional missense variants of HOXB13 have been observed, only G84E has been established to be associated with prostate cancer risk among men of European ancestry." (PMID 34059701, 2021). "The G84E germline mutation of HOXB13 predisposes to prostate cancer and is clinically tested for familial cancer care." (PMID 34059701, 2021). "The Philadelphia Prostate Cancer Consensus has proposed that all male HOXB13 pathogenic variant carriers are offered surveillance with PSA tests from not later than 40 years of age." (PMID 34711244, 2021). "The G84E variant of HOXB13 was identified by sequencing the 17q21–22 region in four families with pedigrees strongly indicative of hereditary prostate cancer predisposition." (PMID 33947030, 2021). "For example, we show that individuals in the male cohort with substantial damage to HOXB13 have an increased risk of prostate cancer (20.7%, compared to 5.9% in the rest of the male cohort)." (PMID 34290314, 2021). "The SE-associated lineage-specific machinery of ERG is linked with the TFs like FOXA1 and HOXB13, which play important roles in prostate-cancer-specific gene expression." (PMID 33299103, 2020). "Germline HOXB13 G84E mutation has been consistently associated with prostate cancer (PCa) risk, but its association with other cancers is controversial." (PMID 32830201, 2020). "A follow-up meta-analysis looking at 25 case-control studies with a total of over 145,000 patients confirmed the increased risk for prostate cancer in HOXB13 G84E mutant carriers (OR 3.248; 95% CI, 2.313–4.560; p < 0.001)." (PMID 32197306, 2020). "Although HOXB13 plays an important role in both breast and prostate cancer progression, germline mutations in the HOXB13 gene seem to associate with the development of prostate cancer only." (PMID 32546843, 2020). "Homeobox B13 (HOXB13), a DNA-binding transcription factor, is overexpressed in castration-resistant prostate cancer and causes the zinc concentration to fall." (PMID 32340289, 2020). "Analysis of familial risk models has revealed the importance of HOXB13 G84E mutations in the development of early-onset prostate cancer." (PMID 32197306, 2020). "HOXB13 expression has been linked to robust cell growth and migration in response to androgens in prostate cancer cells and HOXB13 has been identified as an androgen receptor-interacting protein." (PMID 30866492, 2019). "In particular, the rare, but recurrent HOXB13 G84E mutation is strongly associated with an increased risk of familial prostate cancer in European descents and subsequently found to be highly associated with prostate cancer risk in additional populations." (PMID 31013831, 2019). "This information can be used to assess more personalised prostate cancer risks to men who carry HOXB13 mutations and hence better counsel them on more personalised risk management options, such as tailoring prostate cancer screening frequency." (PMID 30527799, 2019). "In prostate cancer, NGS of linkage regions on chromosome 17 helped to identify a mutation in the homeobox gene HOXB13 as a prostate cancer driver and potential therapy target." (PMID 35582724, 2019). "The homeobox B13 (HOXB13) G84E mutation has been recommended for use in genetic counselling for prostate cancer (PCa), but the magnitude of PCa risk conferred by this mutation is uncertain." (PMID 30527799, 2019). "Men who carry a hereditary mutation in the homeobox B13 (HOXB13) gene have a higher than average risk for developing prostate cancer." (PMID 30527799, 2019). "The prostate cancer risk-associated T allele at rs339331 increases chromatin binding of HOXB13 to an active transcriptional enhancer, conferring allele-specific upregulation of the target gene, RFX6." (PMID 31013831, 2019). "Two additional HOXB13 F127C and G132E mutations were identified among Japanese men with prostate cancer." (PMID 31013831, 2019).
prostate carcinoma (continued). "The HOXB13 G135E mutation was discovered in association with increased prostate cancer risk of Chinese men." (PMID 31013831, 2019). "Together, this study presented the first example of a regulatory risk SNP being responsible for prostate cancer pathogenesis through cooperation with the prostate-lineage-specific transcription factor, HOXB13, to regulate a novel oncogene, RFX6." (PMID 31013831, 2019). "For example, missense germline HOXB13 mutations have been associated with early-onset prostate cancer, breast cancer, and colorectal cancer." (PMID 30866492, 2019). "Remarkably, the inherited mutations in HOXB13 have been widely observed for a genetic contribution to prostate cancer risk." (PMID 31013831, 2019). "One example is the SNP rs138213197, a rare variant causing amino acid change of G84E in HOXB13, which frequently appears in DNA samples of 94 families with hereditary prostate cancer." (PMID 28598379, 2017). "AR is targeted by anti-androgenic therapies used for the treatment of prostate cancer and in tumors cooperates with HOXB13, a gene that when mutated causes predisposition to prostate cancer." (PMID 29312534, 2017). "A rare mutation in the HOXB13 gene, G84E, is reproducibly associated with a 4- to 8-fold increased risk of prostate cancer." (PMID 28186998, 2017). "Similar to this finding, our previous studies found that the prostate cancer risk-associated T allele of SNP rs339331 increases the expression of oncogene RFX6 by disrupting the binding of transcription factor HOXB13." (PMID 28598379, 2017). "A recurrent germline mutation (G84E) in the HOXB13 gene is associated with early onset and family history-positive prostate cancer in patients of European descent, occurring in up to 5% of prostate cancer families." (PMID 28186998, 2017). "The aim of this study was to evaluate the diagnostic sensitivity of HOXB13 in comparison to commonly used immunohistochemical markers for prostate cancer." (PMID 28555048, 2017). "Mutations in the HOXB13 gene have been shown to be associated with prostate cancer development in mouse models and more specifically an androgen-independent phenotype." (PMID 28031937, 2016). "The recurrent germline mutation HOXB13 p.(Gly84Glu) (G84E) has recently been identified as a risk factor for prostate cancer." (PMID 28050579, 2016). "With the recent description of HOXB13 germline mutations predisposing to prostate cancer development, the relevance of HOXB13 for prostate carcinogenesis gained a new perspective." (PMID 28050579, 2016). "We conclude that the HOXB13 A128D and F240L variants identified in Portuguese patients with early-onset/hereditary prostate cancer show oncogenic mechanisms more consistent with gain of function mutations." (PMID 28050579, 2016). "This association between the HOXB13 G84E variant and an increased prostate cancer risk has been confirmed by other groups." (PMID 28050579, 2016). "In a large study performed by the ICPCG consortium, 5% of Europeans with prostate cancer carried the HOXB13 variant, and it is particularly prevalent in Nordic countries where the frequency can be as high as 22%." (PMID 28031937, 2016). "Germline HOXB13 G84E mutation (rs138213197) has been described associated with prostate cancer (PCa) susceptibility but results of different studies are inconsistent." (PMID 27626483, 2016). "Although data from twin studies showed that the genetic contribution to PCa risk is approximately 40%, only a few mutations in genes such as BRCA1, BRCA2, and HOXB13 definitely account for a small proportion of cases of hereditary prostate cancer." (PMID 26967244, 2016). "When we stratified by cancer type, there is significant heterogeneity was existed (I2 = 68.4%, Pheterogeneity < 0.0001) and then random-effect models was used to verify the relationship between HOXB13 p.Gly84Glu mutation and prostate cancer risk." (PMID 26517352, 2015).